TMEM178B (transmembrane protein 178B)
Synonyms: DKFZp547G036
Tractability: Antibody: UniProt predicts a signal peptide or a membrane-spanning region. PROTAC: its protein half-life has been measured.
Gene: Protein-coding gene on chromosome 7 (141,074,064 to 141,480,380, forward strand). Ensembl gene ENSG00000261115.
Subcellular location: Membrane
Subcellular location (Human Protein Atlas): Vesicles; Nucleoli
Gene Ontology:
Molecular function: protein binding
Cellular component: membrane
Genetic constraint (gnomAD): Loss-of-function variants: 4 observed, 21.26 expected, observed/expected ratio (o/e) 0.19, 90% interval 0.092 to 0.43. The upper end of that interval is the gene's LOEUF score, 0.43, which puts it in group 1 of 6, group 1 being the genes least tolerant of losing a copy. Missense variants: 148 observed, 231.97 expected, observed/expected ratio (o/e) 0.64, 90% interval 0.56 to 0.73. Synonymous variants: 89 observed, 93.51 expected, observed/expected ratio (o/e) 0.95, 90% interval 0.8 to 1.13.
Homologues: Orthologues: chimpanzee TMEM178B (100% identical), macaque TMEM178B (99% identical), mouse Tmem178b (99% identical), rat Tmem178b (99% identical), dog TMEM178B (99% identical), pig TMEM178B (99% identical), tropical clawed frog tmem178b (90% identical), zebrafish tmem178bb (85% identical), zebrafish tmem178ba (75% identical). Paralogues in human: TMEM178A (47% identical).
Diseases named in the same sentence as TMEM178B in open-access papers:
TMEM178B is named in the same sentence as 15 diseases in open-access papers, as found by Europe PMC text mining. Sharing a sentence is not in itself a finding about the gene and the disease. The quoted sentences say what the papers report.
cutaneous melanoma (1 paper, 2019). A primary melanoma arising from atypical melanocytes in the skin. "Furthermore, TMEM178B-BRAF gene fusions were identified in two primary mucosal malignant melanoma cases, which are more aggressive than cutaneous melanomas." (PMID 32039202, 2019).
gastric cancer (1 paper, 2020). A primary or metastatic malignant neoplasm involving the stomach. "At last, the four genes, DTNA, PRR11, TMEM178B, and CACNA1D, were mainly related to gastric cancer or prostate cancer." (PMID 32964043, 2020).
rectal cancer (1 paper, 2022). A primary or metastatic malignant neoplasm that affects the rectum. "Non targeted novel fusions were also identified including FGFR1-NRG1 in breast, BRAF-MRPS33 in prostate, SND1-MET in lung, PCM1-BRAF in sarcoma and TMEM178B-MET in rectal cancer." (PMID 35984852, 2022).
tumor (3 papers, 2020 to 2025). "Other low frequency actionable fusions namely, AGK-BRAF, FIP1L1-PDGFRA, FNDC3B-PIK3CA, RET-NCOA4, SND1-BRAF, TMEM178B-MET, TMEM178B-BRAF, KANK1-NTRK3, EIF3E-RSPO2 and PTPRK -RSPO3 have been previously reported as rare fusions in tumours of other type." (PMID 35984852, 2022).
cancer (2 papers, 2020 to 2021). A tumor composed of atypical neoplastic, often pleomorphic cells that invade other tissues. "Notably, the upregulation of TMEM178B and ZNF723 has not been directly linked to carboplatin resistance, and understanding of their biological function in cancer remains limited." (PMID 34440225, 2021).
TMEM178B also shares sentences with these, for which no sentence is quoted: atherosclerosis (1 paper); biliary atresia (1); episodic ataxia (1); leukemia (1); liver fibrosis (1); lung carcinoma (1); malignant melanoma (1); prostate carcinoma (1); sarcoma (1); squamous cell lung carcinoma (1).